PARP1 (poly(ADP-ribose) polymerase 1)
Diseases named in the same sentence as PARP1 in open-access papers (continued):
Sharing a sentence is not in itself a finding about the gene and the disease.
leukemia (52 papers, 2013 to 2026). A malignant (clonal) hematologic disorder, involving hematopoietic stem cells and characterized by the presence of primitive or atypical myeloid or lymphoid cells in the bone marrow and the blood. "The aim of the present study was to determine the underlying molecular mechanisms by which the PARP-1 inhibitor Olaparib enhances the chemosensitivity of the leukemia cell line K562 and THP1 to IDA." (PMID 35130631, 2022). "This information is reassuring regarding the feared risk of myelodysplasia/leukemia reported with PARP1 inhibitors, but, at the same time, indicates that tumor-specific neoantigens are unlikely to be generated with this combination." (PMID 34944915, 2021). "Similarly, the simultaneous inhibition of Polθ with PARP1 or RAD52 was performed in a study on HR-deficient leukemias and showed a strengthened antileukemia effect, in comparison to the separate use of Polθi." (PMID 39273083, 2024). "BRCA2 deficiency may predispose leukemia cells to synthetic lethality triggered by PARP1 inhibitors." (PMID 31537905, 2020). "Evidence that BRCA/DNA-PK-deficient CML leukemia stem cells are highly sensitive to inhibitors of poly-(ADP-ribose) polymerase 1 (PARP1) brought about a potential of targeting key DNA repair enzymes in CML, which are in synthetic lethal relationship with BCR-ABL." (PMID 32272770, 2020). "The chromatin-associated enzyme PARP1, which is one of the core directors of DNA repair and involved in tumorigenesis pathways, was over-expressed in many of the cancer types, such as breast, uterine, ovarian, colorectal, lung, leukemia, and lymphomas at the mRNA and/or protein levels." (PMID 30020984, 2018). "In a mouse model of human acute myeloid leukemia transplantation, the knockout or inhibition of PARP1 can induce the expression of NKG2D ligands on drug-resistant leukemia stem cells." (PMID 38111536, 2023). "PARP1 is also involved in malignant tumors development and resistance of cancers, and it is regarded as a potential therapeutic target in certain leukemia." (PMID 36257929, 2022). "We then used the PARP-1 inhibitor Olaparib to treat leukemia K562 cellsin vitro, either alone or combined with IDA." (PMID 35130631, 2022). "In conclusion, we demonstrated that APO866 induces the production of high levels of various types of ROS/RNS that depend on PARP1 integrity and playing a crucial role in its anti-leukemia activity." (PMID 31803365, 2019). "In fact, PARP1 overexpression has been found to block differentiation in response to all-trans retinoic acid (ATRA) in leukemia cell lines and a reduction of PARP1 expression was observed during differentiation of neutrophils or monocytes." (PMID 31527467, 2019). "PJ34 significantly decreases APO866-mediated cell death in dose-dependent manner, suggesting the implication of PARP1 activation in the anti-leukemia effects of the NAMPT inhibitor." (PMID 31803365, 2019). "Next, we evaluated the ability of etoposide (a PARP1 activating drug through topoisomerase II inhibition) to sensitize leukemia cells to APO866." (PMID 31803365, 2019). "In two representative samples, western blotting confirmed that AG1024 + U0126 + IR induced caspase- and PARP1-dependent apoptosis to a greater extent than the single most potent inhibitor for each leukaemia." (PMID 29656114, 2018). "It has been reported that curcumin induced apoptosis in leukemia cells by PARP-1 cleavage, increased level of caspase-3, apoptosis inducing factor (AIF) and down-regulation of Bcl212." (PMID 28566729, 2017). "In our study, we tested several dysregulated genes associated with leukemia by microarray data analysis, including MPL, GADD45g, TOB1, SLA, and ETS1, and mainly focused on MPL, which was reduced by PARP-1 inhibition." (PMID 26314963, 2015).
leukemia (continued). "The PARP-1 cleavage band at 89 kDa was observed in lysates from leukemia cell lines after 24 h of drug exposure, while it was undetectable in cells treated with only DMSO 0.1 %." (PMID 26542114, 2015). "Others have reported that the HDACi trichostatin A increased protein acetylation and trapped PARP1 to double-strand DNA breaks in the K562 leukemia cell line, and the combination of HDACi with talazoparib resulted in a dose-dependent increase in PARP1 trapping, which correlated with apoptosis." (PMID 39273190, 2024). "In addition, ABL1 kinase phosphorylates and regulates the activity of two DNA repair enzymes, PARP1 and RAD52, inhibition of which triggered synthetic lethality in BRCA1/2-deficient leukemia cells." (PMID 36959186, 2023). "This process could be abrogated by the combined effects of SAHA and Ola through inhibition of PARylation via PARP1 trapping to chromatin, a mechanism that explains the cytotoxicity of the HDACi trichostatin A and the PARPi talazoparib in leukemia cells." (PMID 38074694, 2023). "Treatment with a PARP1 inhibitor and NK cell transfer can inhibit leukemia in mouse models." (PMID 35355427, 2022). "In addition, knockdown of LINC00152 can inhibit PARP1 expression to improve the sensitivity of leukemia cells to chemotherapy, thus improving the prognosis of leukemia patients." (PMID 36033524, 2022). "Both quiescent and proliferating leukemia cells are sensitive to PARP1 inhibitors." (PMID 34732266, 2021). "Moreover, in the case of the multidrug-resistant leukemia cell line HL-60[R] the PARP1 mRNA expression level was up-regulated." (PMID 34207065, 2021). "Furthermore, PARP1-dependent JNK1 activation was essential for TNFα/ATRA-induced apoptosis in NF-κB repressed human leukemia cells, further highlighting the interplay between TNFR and PARP1/JNK1-mediated cell death." (PMID 34725336, 2021). "Finally, PARP1 activating chemotherapeutic drugs strongly potentiate the anti-leukemia activity of APO866." (PMID 31803365, 2019). "PARP1 deletion fully prevented caspase activation and ATP loss in APO866-treated leukemia cells." (PMID 31803365, 2019). "Collectively, these data indicate that PARP1 activating drugs could potentiate the anti-leukemia activity of APO866." (PMID 31803365, 2019). "We show that etoposide sensitizes leukemia cells to APO866 via PARP1 status." (PMID 31803365, 2019). "Therefore, we hypothesized that PPFIA1 contributes to leukemia growth through an axis involving PARP1, P65, and KIT." (PMID 30825668, 2019). "Instead of inhibiting PARP using an inhibitor, we crossed Parp1 knockout mice with BCR/ABL1 Tg mice and examined leukemia development and death." (PMID 37165001, 2023). "The expression of proteins related to apoptosis and autophagy, including cleaved-PARP-1, Bcl-2, Bax, LC3-I/II, Beclin-1, Atg5, p62, phospho-AMPK, AMPK, phospho-mTOR, mTOR, phospho-Akt, and Akt, in human leukemia cells were evaluated using Western blotting." (PMID 36826047, 2023). "The externalization of phosphatidylserine was accompanied by the detection of cleaved PARP1 and the activation of caspase-3 and -7 in the two HAP-1 leukemia cell lines, but these attributes were less apparent in the A2780 and Siso solid tumor cell lines." (PMID 34299253, 2021). "Myc plays a key role in increasing the A-EJ activity in TK-activated leukemia through transcriptional and post-transcriptional changes in Lig III and PARP1." (PMID 34732266, 2021). "We have examined a large number of cancer and normal cells of various origins (kidney, breast, ovarian, prostate, and leukemia) for aberrations in the poly(ADP-ribosyl)ating pathway, including PARP-1 protein and PARG enzyme." (PMID 34638458, 2021).
leukemia (continued). "The present study also highlights the role of PARP1 in oxidative stress production, the cumulative anti-leukemia potentials of APO866 and chemotherapeutic drugs that active PARP1, such as etoposide." (PMID 31803365, 2019). "To complement the pharmacological PARP1 inhibition and to verify its contribution in the anti-leukemia effects of APO866, we generated PARP1 knockout Jurkat cells." (PMID 31803365, 2019). "The HDACi trichostatin A increased acetylation of DNA repair factors and impaired the non-homologous end joining (NHEJ) DNA repair pathway, and addition of talazoparib enhanced trapping of PARP1 to DSBs leading to decreased NHEJ and leukemia cell death." (PMID 29423093, 2018). "Luteolin increased the cell population in the sub-G1 phase and the levels of apoptotic protein markers, including cleaved caspase 3 and PARP1, in THP-1 leukemia cells." (PMID 29649138, 2018). "In leukemia and NSCLC cell lines, the combination of JL189 with ABT-263 after 5 hr induced a much greater increase in the expression of activated caspase-3 fragment and cleavage of PARP-1 compared to each compound alone." (PMID 39315260, 2024). "Therefore, PARP1 inhibition by olaparib and talazoparib (BMN-673) in MLL-AF9 leukemia cells increases the number of DSBs, the rate of cell death, and treatment efficacy in combination with conventional therapies." (PMID 34732266, 2021). "We show that the chemotherapeutic drug, etoposide, that activates PARP1, or exogenous supplementation with H2O2 could be a successful strategy to sensitize leukemia cells to APO866." (PMID 31803365, 2019). "Finally, PARP2 but not PARP1, was found to localize to ALT-associated promyelocytic leukemia bodies (APBs), which are the DNA synthesis centers of ALT cells." (PMID 38565848, 2024). "Finally, to assess whether sensitization of leukemia cells to APO866 by etoposide involves PARP1 activity, PARP1-KO malignant cells were exposed to etoposide alone or etoposide plus APO866 for 96 hours before assessing their viability." (PMID 31803365, 2019). "Interestingly, in NALM6 leukemia cells, the level of DNA damage was also high (~15–25%) despite no statistically significant degradation of PARP1 polymerase; it is possible that after an extended incubation period without the presence of test compounds, some of this DNA damage would be repaired." (PMID 37175377, 2023).
Parkinson disease (49 papers, 2009 to 2026). A progressive degenerative disorder of the central nervous system characterized by loss of dopamine producing neurons in the substantia nigra and the presence of Lewy bodies in the substantia nigra and locus coeruleus. "Here we report that RNF146 expression and RNF146 inducers can prevent cell death elicited by Parkinson’s disease (PD)-associated and PARP1-activating stimuli." (PMID 29290984, 2017). "Furthermore, an in vivo study has shown that PARP1 activation is associated with the pathogeneses of Alzheimer’s disease and Parkinson’s disease, indicating that PARP1 deficiency prevents brain dysfunction and cognitive decline." (PMID 38921477, 2024). "Parkinson’s disease is caused by an accumulation of fibrillary α-synuclein (α-syn) and is associated with elevated levels of oxidative stress and likely the activation of PARP-1." (PMID 35158955, 2022). "It has been reported in Science that strategies aimed at inhibiting PARP-1 activation could hold promise as a disease-modifying therapy to prevent the loss of dopamine neurons in Parkinson’s disease and related a-synucleinopathies." (PMID 35317687, 2022). "It has been reported that hyperactivation of PARP-1 plays an important role in the development of diseases directly or indirectly associated with chronic inflammation, including diabetes, neurodegenerative disorders (Alzheimer’s disease (AD), Parkinson’s disease (PD)), and cardiovascular diseases." (PMID 36946488, 2023). "Cleavage of PARP-1 by caspases is considered to be a hallmark of apoptosis and has been implicated in several neurological diseases like Alzheimer’s disease, cerebral ischemia, multiple sclerosis, traumatic brain injury, Parkinson’s disease, NMDA-mediated cytotoxicity and brain tumors." (PMID 35432810, 2021). "A recent study identified DJ-1 as a regulator of PARP1, linking oxidative-stress sensing to DNA repair in Parkinson’s disease." (PMID 41369348, 2025). "Both continuous oxidative stress and poly (ADP-ribose) polymerase 1 (PARP-1) activation occur in neurodegenerative diseases such as Parkinson’s disease." (PMID 38476326, 2024). "The deletion of the gene coding for poly(ADP-ribose) polymerase-1 (PARP1) or its pharmacological inhibition protects mice against cerebral ischemia and Parkinson's disease." (PMID 36743979, 2023). "In neurodegenerative disorders including Parkinson’s disease and multiple sclerosis, hyperactivation of PARP-1 results in neuronal death via accumulation of PAR polymers as well as excessive glial cell activation." (PMID 37924373, 2023). "The increase in PARP1 activity and the associated reduction in cellular NAD pools was also shown in Alzheimer’s and Parkinson’s disease models." (PMID 37174729, 2023). "Many PARP1 inhibitors (oxaliplatin, PJ-34, 3-aminobenzamide, olaparib) have been studied in stroke, Parkinson’s disease (PD), Alzheimer’s disease (AD), Huntington’s disease (HD), and amyotrophic lateral sclerosis (ALS), but have not been clinically evaluated." (PMID 35806303, 2022). "One such example is where PARP1 inhibition initiated prevention of neurodegeneration seen during Parkinson’s disease, by restoring degradation of alpha-synuclein." (PMID 33805567, 2021). "PARP1-mediated cascade of progression to neurodegeneration and neuroinflammation has been shown in Parkinson’s and Alzheimer’s disease." (PMID 33405206, 2021). "Research is also underway on the use of PARP-1 inhibitor in treatment other diseases, among others multiple sclerosis, rheumatoid arthritis, myocardial infarction, stroke, acute neuroinjury, and Parkinson’s disease." (PMID 33572586, 2021). "For instance, it has recently been demonstrated that increased expression of PARP1, a well-known anti-apoptotic cancer target, plays a role in neuronal cell death in Parkinson’s disease." (PMID 32066498, 2020).
Parkinson disease (continued). "PARP-1 is also involved in neurodegenerative diseases characterized by cytotoxic protein aggregates, including Parkinson’s disease (PD) and Alzheimer’s diseases (AD)." (PMID 31877876, 2019). "Beyond the role of PARP1 in oncology, emerging research has indicated its potential as a therapeutic target against Alzheimer's disease and Parkinson's disease, which have been shown to upregulate PARP1 and lead to neuroinflammation, mitochondrial dysfunction, and autophagy dysregulation." (PMID 38258328, 2024). "A better definition of these mechanisms will be central to clarify the contribution of PARP1-dependent cell death to human pathology, particularly in a variety of neurodegenerative disorders, such as Parkinson’s and Alzheimer’s disease, which are of rising concern in an aging human population." (PMID 39356140, 2024). "PARP1 is primarily identified as a target in oncology yet recent studies have also suggested it as a potential target against ageing and neurodegenerative diseases such as Alzheimer's disease and Parkinson's disease." (PMID 38258328, 2024). "Additionally, PARP1 was previously reported to play an essential role in neurodegenerative diseases such as AD and Parkinson’s disease." (PMID 36399449, 2022). "Moreover, increased expression and excessive activation of PARP1 was demonstrated in Parkinson’s disease, Alzheimer’s disease and amyotrophic lateral sclerosis." (PMID 34206738, 2021). "Consequently, we examined whether DX2 competes with AIMP2 for PARP-1 activation and is therapeutically effective in Parkinson’s disease." (PMID 38172953, 2024). "Indeed, PARP-1 inhibitors are noted to demonstrate neuroprotective effects in demyelinating disorders such as multiple sclerosis and Parkinson’s disease, further supporting the use of these drugs in demyelinating, neuroinflammatory, and neurodegenerative diseases." (PMID 35158955, 2022). "As it was demonstrated, Aβ and α-synuclein accumulation may generate activation of PAPR1 via, for example, increased level of ROS; thus, enhanced PARP1 activity aggravates Alzheimer’s disease and Parkinson’s disease symptoms by promotion of Aβ and α-synuclein aggregation, respectively." (PMID 34206738, 2021). "Poly(ADP-ribose) polymerase-1 (PARP-1) activation and α-synuclein (α-syn) aggregation are neuropathological hallmarks of Parkinson's disease." (PMID 42051564, 2026). "The genetic markers of Parkinson’s disease BCL2, TBP,and TAF1 exert greater regulatory influence on acylcarnitinemetabolism enzymes, while PARP1 equally affects enzymesinvolved in both amino acid and acylcarnitine metabolism." (PMID 39944797, 2024). "Parthanatos represents a critical molecular aspect of Parkinson's disease, wherein AIMP2 aberrantly activates PARP-1 through direct physical interaction." (PMID 38172953, 2024). "Thus, while PARP-1 inhibition may promote cell lethality through excessive DNA damage in cancer therapy, prudent PARP-1 suppression could offer a therapeutic avenue to regulate abnormal neuronal death in conditions such as Parkinson's disease (PD) and ischemia." (PMID 38172953, 2024). "In a rodent model of Parkinson's disease (PD), recombinant α-synuclein preformed fibrils (α-syn PFF) induced the activation of PARP1, which promoted the formation of more pathologic α-syn aggregates that eventually led to cortical neuronal death." (PMID 36438061, 2022). "Inhibition of PARP1 promotes TFEB‐mediated autophagy and then increases the degradation of α‐synuclein, providing a potential therapeutic strategy of Parkinson’s disease." (PMID 32475059, 2020). "In fact, PARP-1-/- mice confirm the protective role of PARP-1 deficit towards injury induced by Aβ injections (that mimics Alzheimers disease), MPTP or 6-OHDA (used to induce Parkinson-like symptoms)." (PMID 28503382, 2017).
Parkinson disease (continued). "Since none of the mouse models of Parkinsonism, induced by a neurotoxin, could explain PD symptoms completely, we confirmed that the chemicals effectively induced aberrant activation of PARP-1." (PMID 38172953, 2024). "Thus, inhibitors of PARP1 or CD38 were used to prevent the reduction in cellular NAD pools during pathologic conditions such as ischemia and traumatic brain injury, or in models of Alzheimer’s and Parkinson’s disease." (PMID 37174729, 2023).